CDH11 (cadherin 11)
Diseases named in the same sentence as CDH11 in open-access papers (continued):
Sharing a sentence is not in itself a finding about the gene and the disease.
prostate carcinoma (continued). "Additionally, cadherin-11 is expressed in several types of cancer including breast and prostate cancers, osteosarcoma, and colon cancer." (PMID 19274078, 2009). "Moreover, a previous report revealed that AmotL1 is critical for cadherin-11-mediated cell migration and may be involved in promoting migration in prostate cancer." (PMID 30531834, 2019). "Therefore, the expression of both N-cadherin and cadherin 11 or the potential interactions between these two distinct cadherins may be essential for prostate cancer cell migration." (PMID 23359820, 2013). "CXCR7 has been reported to influence adhesion in multiple cell types and can specifically regulate cadherin 11 and CD44 in prostate cancer cells." (PMID 25084358, 2014). "N-cadherin and cadherin-11 are highly expressed in prostate cancer cells and osteoblasts, but not in normal prostate tissue." (PMID 21206493, 2011).
rheumatoid arthritis (18 papers, 2009 to 2026). A chronic, systemic autoimmune disorder characterized by inflammation in the synovial membranes and articular surfaces. "Cadherin-11 (CDH11), associated with epithelial to mesenchymal transformation in development, poor prognosis malignancies and cancer stem cells, is also a major therapeutic target in rheumatoid arthritis (RA)." (PMID 24681547, 2014). "CDH11 has demonstrated important functions in rheumatoid arthritis (RA) fibroblast-like synoviocytes (FLS)." (PMID 40877928, 2025). "Among these promoters, cadherin-11 (Cad11) is a cell–cell adhesion protein related to inflammation in rheumatoid arthritis." (PMID 38540696, 2024). "Cdh11 transcripts have been previously found in the peripheral blood as indicators of severe disease as in rheumatoid arthritis." (PMID 37954069, 2023). "CDH11 is already a therapeutic target in rheumatoid arthritis, an inflammatory disease with properties shared with cancer." (PMID 32665033, 2020). "Systemic administration of anti-CDH11 antibodies restricts the proliferation and migration of synoviocytes to inflammatory joints and decreases the symptoms of rheumatoid arthritis." (PMID 32665033, 2020). "In rheumatoid arthritis, matrix metalloproteinases (MMPs)- and γ-secretase- induced cleavage induced CDH11 activity, through its release from the cytoplasmic domain and subsequent nuclear translocation." (PMID 30691241, 2019). "Among the genes with the peak expression in the mid-pregnancy followed by a drop at term, BMP5, CDH11 and FST are implicated in bone and cartilage related disorders such as rheumatoid arthritis and osteoarthritis." (PMID 23145134, 2012). "The cadherin-11 knockout mouse exhibits bone and behavioral abnormalities and is resistant to induction of rheumatoid arthritis." (PMID 19274078, 2009). "The cell-cell adhesion molecule cadherin-11 is important in embryogenesis and bone morphogenesis, invasion of cancer cells, lymphangiogenesis, homing of cancer cells to bone, and rheumatoid arthritis." (PMID 19274078, 2009). "Cadherin-11 is also expressed in cartilage synoviocytes and is an important mediator of the synoviocyte reaction that characterizes rheumatoid arthritis." (PMID 19274078, 2009). "This study aimed to determine whether umbilical cord-derived mesenchymal stem cells (UCMSC) regulate Cadherin-11 (CDH11) expression by fibroblast-like synoviocytes (FLS) in rheumatoid arthritis (RA)." (PMID 26090476, 2015). "Furthermore, in rheumatoid arthritis CDH11 modulates synovial fibroblasts to evoke inflammatory factors and targeting CDH11 by mAb directed against CDH11 significantly reduced inflammation." (PMID 25546151, 2014). "Being a mediator of EMT in the development of organ fibrosis and a contributor to the inflammatory process in rheumatoid arthritis, it could be hypothesized that CDH11 is a newly identified candidate therapeutic target for fibrosis in IBD." (PMID 25546151, 2014). "Importantly, CDH11 is a therapeutic target in rheumatoid arthritis (RA), an inflammatory disease with properties often compared with cancer." (PMID 24681547, 2014). "Interestingly, in vivo studies have demonstrated that cadherin-11 deficient mice have an attenuation in synovial inflammation in the KBxN serum transfer arthritis model, suggesting that cadherin-11 may be a therapeutic target for human inflammatory arthritis, such as rheumatoid arthritis." (PMID 24917820, 2014). "Furthermore, cadherin-11 is a therapeutic target in rheumatoid arthritis (RA) patients." (PMID 31373305, 2019).
Arthritis (17 papers, 2014 to 2026). Inflammation of a joint. "CDH11 is critical for lining layer formation and CDH11 deficient mice are resistant to arthritis induction; and has been explored as a therapeutic target." (PMID 35252279, 2022). "Cadherin 11 also represents a potential candidate to control the altered behaviour of fibroblasts in several pathologies such as arthritis and fibrosis." (PMID 36926329, 2023). "Increasing lines of researches have proved that CDH11 plays important roles in the occurrence and development of a lot of diseases, such as tumors, arthritis and so on." (PMID 33442417, 2021). "Lee et.al found that anti-Cadherin-11 displays moderate amelioration of established K/BxN serum transfer arthritis." (PMID 31829201, 2019). "The protective effect of anti-Cadherin-11 therapy has been demonstrated convincingly in a range of arthritis models." (PMID 31829201, 2019). "Specifically, cadherin-11 was found to be pivotal for the invasive potential of inflammatory synovial fibroblasts and blockage of the cadherin-11 accordingly ameliorated cartilage destruction in experimental arthritis model." (PMID 35547214, 2022). "More and more studies have showed that CDH11 plays important roles in the process of tumor, metabolic diseases, arthritis, skin diseases and other diseases, and may be a potential therapeutic target." (PMID 33442417, 2021). "Indeed, blockade of CDH11 attenuates inflammation in mouse models of arthritis, an effect that may be due in part to reduced IL-6 production by CDH11+ synovial fibroblasts." (PMID 31156640, 2019). "Of them, circulating fibroblasts (podoplanin+CD45-CD3-CD19-CD4-CD8-CD56-CD66b-CD294-) co-expressing CDH11 and C-C Chemokine Receptor 7 (CCR7) were found exclusively in arthritis patients' blood." (PMID 41624850, 2026). "CDH11 has been suggested to be involved in the pathogenesis of RA, as CDH-11-null mice show reduced arthritis activity." (PMID 38891047, 2024). "A previously published study stated that the relative abundance of gut Candidatus_Saccharimonas was negatively correlated with the expression levels of cadherin-11, IL-17α, and TLR2 in the adjuvant-induced arthritis rat model." (PMID 34956162, 2021). "One of the relatively unique surface markers for RA-FLS is cadherin-11 (CDH11), which plays an essential role in the acquisition of the invasive phenotype of activated FLS in arthritis." (PMID 27430622, 2016). "The repurposed arthritis drug celecoxib, which binds to CDH11, and other small molecules designed to bind CDH11 without inhibiting COX-2 preferentially affect the growth of CDH11 positive cancer cells in vitro and in animals." (PMID 24681547, 2014). "IL-10 mediates the inhibitory effect of UCMSC on CDH11 expression by FLS, and this mechanism might be targeted to ameliorate arthritis." (PMID 26090476, 2015). "IL-10 mediates the inhibitory effect of UCMSC on CDH11 expression by FLS from RA patients, and this mechanism might be targeted to ameliorate arthritis." (PMID 26090476, 2015).
gastric cancer (17 papers, 2016 to 2025). A primary or metastatic malignant neoplasm involving the stomach. "Other highly correlated genes that have previously been implicated in gastric cancer included CDH11, MSRB3 and FSTL1." (PMID 35406381, 2022). "Comprehensive evaluation of metastasis and invasion pathway identified a subset of associated genes and confirmed PLAUR and CDH11, both targets of miR-335, to be overexpressed in gastric cancer tissues." (PMID 29075357, 2017). "Our previous study reported that CDH11-mediated juxtacrine interaction of gastric cancer cells and fibroblasts promotes metastasis via YAP/tenascin-C." (PMID 38462626, 2024). "In the early stage, we also reported the relationship between CDH11 and malignant progression of gastric cancer through the public cancer database." (PMID 37552104, 2023). "It has previously been suggested that increased CDH11 expression indicates a poor prognosis in advanced gastric cancer and triple negative breast cancer (TNBC)." (PMID 37954069, 2023). "Collectively, these data demonstrate that CDH11 was upregulated in gastric cancer and as an oncogene to promote gastric cancer progression via transcriptional regulation by HEYL." (PMID 32463580, 2020). "Several studies have highlighted the clinical implications and molecular functions of CDH11 in gastric cancer." (PMID 32463580, 2020). "We found that cadherin 11 (CDH11) is highly expressed not only in gastric cancer tissues but also in EMT molecular subtypes and metastatic patients." (PMID 32685527, 2020). "Consistently, overexpression of HEYL strikingly accelerated the gastric carcinoma development through activating oncogenic signaling pathways and transcriptional activation of cadherin 11 (CDH11)." (PMID 32463580, 2020). "CDH11 has been reported deregulated in various tumor types, suggesting a role in tumor invasion, and its overexpression was found in advanced gastric cancer." (PMID 29075357, 2017). "Our comprehensive evaluation of metastasis and invasion pathway led us to identify and confirm that PLAUR, a validated target of miR-335, and CDH11 are overexpressed in gastric cancer tissues." (PMID 29075357, 2017). "Our findings reflected that CDH11 likely plays an important role in tumor immune escape and could provide a prognostic biomarker and potential therapeutic target for patients with gastric cancer." (PMID 32685527, 2020). "Furthermore, CDH11 was regulated by HEYL and rescued oncogenic behavior in HEYL deficient gastric cancer cells." (PMID 32463580, 2020). "Taken together, these data suggest CDH11 as a downstream target of HEYL in gastric cancers." (PMID 32463580, 2020). "Therefore, elucidating the crucial functions and regulatory mechanism of CDH11 in tumor stromal cells in future studies is important for understanding the progression of gastric cancer." (PMID 32463580, 2020). "In vitro experiments showed that CDH11 expression was reduced in the PTX-resistant cancer tissues and a PTX-resistant gastric cancer cell line MKN45P-PR." (PMID 33391403, 2021). "In gastric cancer, exogenous miR-335 decreased migration and invasion of AGS and Hs 746T cells by inhibiting PLAUR and CDH11 genes." (PMID 32974144, 2020). "Also, we found evidences that CDH11 might promote the gastric cancer progression." (PMID 32685527, 2020). "Similarly, in gastric cancer, TSPAN1 appeared to regulate CDH11 expression, which, in turn, mediated the interaction between gastric cancer cells and CAFs." (PMID 40777026, 2025).
pulmonary fibrosis (16 papers, 2013 to 2024). Chronic progressive interstitial lung disorder characterized by the replacement of the lung tissue by connective tissue, leading to progressive dyspnea, respiratory failure, or right heart failure. "CDH11 is linked to fibrotic diseases such as liver fibrosis, scleroderma, and pulmonary fibrosis, and CDH11 is up-regulated by TGFβ2." (PMID 35573666, 2022). "Accordingly, cadherin-11 deficient mice have a significant decrease in dermal and lung fibrosis when challenged with subcutaneous or intratracheal bleomycin." (PMID 24917820, 2014). "TGFβ induces cadherin-11 expression in lung adenocarcinoma cells and this upregulation is required for the EMT response, while on the other hand, mice with a homozygous loss of cadherin-11 present with a relative resistance to pulmonary fibrosis and reduced levels of TGFβ in the lung." (PMID 27367735, 2016). "Moreover, data, from in silico studies on kidney and lung fibrosis, demonstrated that, in these tissues, fibroblasts had a Cadherin-11 upregulation, and furthermore, that the fibroblast invasion during lung fibrosis is directly linked to the cadherin upregulation." (PMID 34439991, 2021). "The process correlates with another target of miR-200c, cadherin 11 (CDH11), which is elevated in lung fibrosis and is related to fibroblast migration, myofibroblast differentiation, and the EMT process during lung injury." (PMID 39727949, 2024). "Our data suggest that CDH11 deficiency impairs the differentiation of CMPs towards the myeloid lineage which results in the production of fewer Ly6Chi monocytes and may lead to the recruitment of fewer monocyte-derived macrophages and attenuation of pulmonary fibrosis in Cdh11-/- mice." (PMID 35211116, 2022). "Our group has previously shown that CDH11 expression is increased in the lungs of patients with idiopathic pulmonary fibrosis and in mice given bleomycin." (PMID 35211116, 2022). "Collectively, our study provides insight into the role of CDH11 in macrophages and pulmonary fibrosis." (PMID 35211116, 2022). "Using flow cytometric analysis, we show that in the IP bleomycin model of pulmonary fibrosis, Cdh11-/- mice have reduced numbers of MoAMs and IMs compared to WT mice." (PMID 35211116, 2022). "In this study, we use the bleomycin-induced pulmonary fibrosis model to investigate the role of CDH11 on macrophage biology." (PMID 35211116, 2022). "Here, we use the intraperitoneal (IP) bleomycin model of pulmonary fibrosis to characterize the macrophage subsets, as well as their monocyte precursors, in the lung tissue of WT and Cdh11-/- mice." (PMID 35211116, 2022). "Cadherin-11 (CDH11) is a cell-cell adhesion protein that has previously been reported to play an important role in the pathogenesis of pulmonary fibrosis." (PMID 35211116, 2022). "Neutralization and genetic deletion of CDH11 reduced lung fibrosis in a model of bleomycin-induced pulmonary fibrosis in mice and skin fibrosis in two different mouse models." (PMID 31269038, 2019). "CDH11 contributes to pulmonary fibrosis by mediating transforming growth factor (TGF)-β-induced EMT and is induced by TGF-β, which is considered a prototypic inducer of EMT." (PMID 25938545, 2015). "Anti-CDH11-neutralizing monoclonal antibodies (mAb) successfully treated established pulmonary fibrosis in mice." (PMID 25546151, 2014). "Using murine models of skin and lung fibrosis, it is now evident that the increase in cadherin-11 in fibrotic tissue, is mechanistically involved in the development of fibrosis." (PMID 24917820, 2014). "We show using immunophenotypic analyses that Cdh11-/- mice have fewer recruited monocyte-derived macrophages and Ly6Chi monocytes in the lungs compared to wild-type mice in the intraperitoneal bleomycin-induced pulmonary fibrosis model." (PMID 35211116, 2022).
pulmonary fibrosis (continued). "We previously showed that CDH11 may be promoting lung fibrosis by regulating the production of TGF-β1 in alveolar macrophages and epithelial to mesenchymal transition (EMT) in alveolar epithelial cells." (PMID 35211116, 2022). "We then investigated whether CDH11 is required for the polarization of M2 macrophages in vivo in the IP bleomycin-induced pulmonary fibrosis model." (PMID 35211116, 2022). "Collectively, our results provide insight into how CDH11 regulates macrophage biology during pulmonary fibrosis and suggests that targeting CDH11 on macrophages could be a viable therapeutic strategy for the prevention and treatment of pulmonary fibrosis." (PMID 35211116, 2022). "Furthermore, we showed that mice deficient in CDH11 or inhibition of CDH11 with neutralizing monoclonal antibodies against CDH11 markedly protected the mice from bleomycin-induced lung fibrosis." (PMID 35211116, 2022). "CDH11 expression is increased in fibrotic skin of scleroderma patients and mouse models of skin fibrosis and in fibrotic lungs of idiopathic pulmonary fibrosis patients and mouse models of pulmonary fibrosis." (PMID 31269038, 2019). "A recent report has confirmed the expression of CDH11 on macrophages and suggested it may promote lung fibrosis through CDH11 mediated contact with fibroblasts." (PMID 31269038, 2019). "Furthermore, an antibody that neutralizes the homotypic interactions between cadherin-11 proteins proved beneficial in reducing pulmonary fibrosis in normal mice." (PMID 27367735, 2016). "The increase in cadherin-11 expression in fibrotic tissue was subsequently confirmed using multiple techniques in systemic sclerosis skin biopsies and fibrotic lung tissue from patients with idiopathic pulmonary fibrosis." (PMID 24917820, 2014). "Moreover, other studies revealed that CDH11 increases in pulmonary fibrosis, and contributes to EMT." (PMID 24702795, 2014). "In pulmonary fibrosis, expression of CDH11 is also increased in wound healing and fibrotic skin." (PMID 25546151, 2014). "More recently, Lodyga and colleagues showed that CDH11 can also mediate the adhesion of macrophages to myofibroblasts which maintains the TGF-β1-producing macrophages in close proximity for persistent activation of the profibrotic myofibroblasts to promote the development of lung fibrosis." (PMID 35211116, 2022). "In addition, CDH11 also plays a role in the development of skin and lung fibrosis." (PMID 31269038, 2019). "Our results supported the roles of CDH11 in inducing the EMT, which corresponded to other research not only in cancer but in other diseases including melasma and pulmonary fibrosis." (PMID 36315446, 2022). "Previous reports support a role for cadherin-11 (CDH11) in regulating the development of dermal and pulmonary fibrosis." (PMID 31269038, 2019). "Pulmonary fibrosis involves both excessive TGFβ signaling and EMT, and lung tissue fibrosis correlates with cadherin-11 (also known as osteoblastic, OB-cadherin) expression." (PMID 27367735, 2016). "Indeed, the current data suggest that CDH11 is upregulated during hepatocyte injury, similar to prior observations of CDH11 on injured type II alveolar epithelial cells in IPF patients and murine bleomycin lung fibrosis." (PMID 31269038, 2019). "Thus, CDH11 is a mediator in EMT and the development of pulmonary fibrosis." (PMID 25546151, 2014). "However, our in vivo data show that CDH11 may not be regulating the M2 program during pulmonary fibrosis." (PMID 35211116, 2022).